CD8A (CD8 subunit alpha)
Diseases named in the same sentence as CD8A in open-access papers (continued):
Sharing a sentence is not in itself a finding about the gene and the disease.
tumor (continued). "In order to narrow the gap between bench and bedside, the clinical potential of CD8α ALN-1 as a therapeutic cancer vaccine adjuvant should therefore be further evaluated in orthotopically growing tumor models and patient-derived xenografts." (PMID 34772757, 2021). "The partial control over tumor growth on treatment with OVA + CD8α ALN-1 was completely lost on CTL depletion." (PMID 34772757, 2021). "TEG011_CD8α-treated mice had a significantly lower tumor burden over time compared to the mock control TEGLM1_CD8α and TEG011-treated groups, indicating superior tumor control in vivo by TEG011_CD8α." (PMID 34759930, 2021). "The MutuDC1 cell line (CD8α+ murine tumor DC line) consists of an immortalized cell line generated through culture of splenic DC tumors from transgenic mice." (PMID 33679743, 2021). "A previous study examined the targeted delivery of α-GalCer to CD8α+ DCs via anti-DEC205 decorated nanoparticles in an attempt to improve iNKT cell-based anti-tumor responses in a murine B16-F10 melanoma model." (PMID 34680322, 2021). "As expected, PD-L1 signal was localized only in neoplastic centroblasts and immunoblasts, whereas PD-1 and CD8A were mainly retrieved in small lymphocytes ascribable to tumor-infiltrating T-cells." (PMID 34209830, 2021). "This study demonstrated that a lower-flexibility of CD8α hinge improved survival under high tumor burden and reduced proinflammatory cytokines in preclinical studies." (PMID 34675920, 2021). "The GZMB/CD8A ratio can reflect the degree of immune cytotoxicity and cytotoxic T lymphocyte infiltration, which can be used to predict the response of tumor genes to immune cells." (PMID 34394706, 2021). "Analysis of tumours from DPX-R9F/CPA/anti-PS treatment resulted in elevated expression of cd8α compared to untreated controls." (PMID 33627686, 2021). "In our lab, a synthetic construct that fused the CD8α extracellular domain to a MyD88 intracellular domain, normally downstream of innate immune receptors, resulted in enhanced anti-tumor CD8 T cell function in mouse models." (PMID 34012443, 2021). "It was shown that intratumoral delivery of MLKL mRNA stimulates anti-tumor immunity against neo-epitopes, a process that was dependent on CD8α+ DCs, which are proficient in antigen cross-presentation." (PMID 33658037, 2021). "The provided TLR7/8 stimulation thereby ensures that pDCs are activated and supports CD8α+ cDC engagement for priming of tumor reactive CD8+ T cells." (PMID 34611284, 2021). "In this regard, CD8α+ pDCs activated by TLR7 ligands were shown to exhibit direct tumor-killing activity mediated by granzyme B. Furthermore, TRAIL-expressing pDCs were shown to be capable of cross-presentation." (PMID 34065346, 2021). "Overall, we demonstrate that TEG011 equipped with human CD8α coreceptor elicits superior tumor control and long-term persistence, which mainly impacted numbers of γδTCR+CD4+CD8+ double-positive TEG011_CD8α cells, and associated with better T-cell infiltration." (PMID 34759930, 2021). "As expected, depleting CD8+ T cells using anti-CD8α mAb prevented tumor rejection on anti-CTLA-4 antibody treatment, indicating that ICI-mediated rejection of YTN16 was dependent on CD8+ T cell responses." (PMID 35008270, 2021). "The elevated activities of CTL and NK cells of splenocytes, as well as the increased infiltration of DCs and CD8a+ T cells into tumor tissue, were also observed with the administration of SART3 micelles." (PMID 33668746, 2021). "Here, we designed a nanoparticle-based vaccine able to target human CD141+ (BDCA3+) DCs - the equivalent of murine CD8α+ DCs – and deliver both tumor Ag (Melan A) and α-GalCer." (PMID 32973811, 2020). "Based on the co-expression correlation between CD274 and CD8A in 29 tumor types, and between GZMA and PRF1 in 32 tumors, we further classified TME into eight groups according to IRGs’ expression level." (PMID 33585244, 2020).
tumor (continued). "Active co-delivery of tumor antigens (Ag) and α-galactosylceramide (α-GalCer), a potent agonist for invariant Natural Killer T (iNKT) cells, to cross-priming CD8α+ dendritic cells (DCs) was previously shown to promote strong anti-tumor responses in mice." (PMID 32973811, 2020). "Other CD8a+-targeting antibody-derived probes have shown similar tumor uptake in syngeneic mouse tumor models." (PMID 32086762, 2020). "The optimal dose of CD8a+-F(ab)′2 for tumor visualization has previously been established in immunocompetent mice by our group." (PMID 32086762, 2020). "(B) Flow cytometric analysis of tumor-infiltrating CD8+ T cells (CD45+CD3+CD8a+ cells) and NK cells (CD45+CD3–NK1.1+ cells) stimulated ex vivo with phorbol 12-myristate 13-acetate and ionomycin for Ifn-γ co-staining." (PMID 32396064, 2020). "Compared to Colon-26, not only MMPs but also T cell surface marker expression, such as CD4 and CD8a, had increased on Colon-26MGS tumor (Table A4)." (PMID 32325684, 2020). "Accordingly, anti-tumor responses, either spontaneous or induced with immune checkpoint therapy, correlate with intratumoral infiltration and maturation of cross-presenting CD8α+CD103+ dendritic cells (DCs)." (PMID 32932620, 2020). "Optimal immune-mediated tumor destruction requires not only the CD8α+ DC lineage but also type I interferon (IFN) signaling." (PMID 33238631, 2020). "In support of the in vitro data, the Siglec-4 spacer CAR displayed a similar anti-tumor efficacy in vivo as the cognate CD8α spacer CAR against TSPAN8 and both therapies were superior to the IgG4-based spacer CAR treatment." (PMID 32849600, 2020). "The median tumor-to-heart ratio was applied to stratify mice into either CD8a low ([64Cu]NOTA-CD8a < 6) or CD8a high ([64Cu]NOTA-CD8a > 6) uptake." (PMID 32086762, 2020). "Flow cytometry and IHC confirmed the increase in tumor-infiltrating CD8a+ cells in XRT + anti-CTLA-4-treated mice." (PMID 32086762, 2020). "By activating cGAS-STING signal in DCs, CD8α+ subtype DCs secret chemokines such as CCL5 and CXCL10 and cross-prime infiltrating anti-tumor CD8+ T cells." (PMID 32411126, 2020). "Further, the increase in the [64Cu]NOTA-CD8a tumor-to-heart ratio in tumors of mice treated with XRT and anti-CTLA-4 matched the increased number of CD45+CD8a+ cells detected by flow cytometry in this treatment group." (PMID 32086762, 2020). "IFN promotes maturation and antigen presentation by CD8α+ dendritic cells (DC) and thus priming and activation of tumor infiltrating CD8 T cells and Natural Killer (NK) cells." (PMID 33552072, 2020). "We further validated the correlation of IDO1/CD8A stratification and cancer progression, and investigated tumor immune status through an in vivo model." (PMID 33425745, 2020). "The tumor burden within the groups treated with the CD8α and Siglec-4 spacer CARs decreased in a comparable manner and reached baseline by the end of the experiment 29 days after T cell injection." (PMID 32849600, 2020). "CD8+ T cell abundance was quantified from tumor RNAseq profiles using a four-gene expression signature score (referred to as TSIG) derived from the geometric mean of the normalized log2 read counts for the genes CD8A, CD8B, CD3D, and CD3E." (PMID 32117236, 2020). "Meanwhile, CD8A and GZMA also had similar expression variants in several tumor types such as COAD, SKCM, STAD, KIRC, and THCA." (PMID 33585244, 2020). "When tumor-derived DNA is delivered to the cytoplasm of CD8α+ dendritic cells (DCs), the STING pathway is activated." (PMID 32596152, 2020). "The diagram explained that nc886 can promote the production of killer T cells (CD8a) due to its restriction for tumor antigen presentation." (PMID 32476259, 2020). "The frequency of CD8a positive cells was assessed on a scale from zero to four within the tumor and stroma compartment separately and the two metrics were added to obtain the overall score." (PMID 31937798, 2020).
tumor (continued). "As the tumor site is additionally an important interaction site for CTLs and MDSCs, we assessed frozen tumor sections for CD8a and IFNγ by immunoflourescent staining." (PMID 32106810, 2020). "Consistent with overexpression of the CD8A gene, Cluster IV had the highest level of immune cytolytic activity among all four clusters and thus had higher anti-tumor efficacy, likely due to T- cell infiltration." (PMID 30847026, 2019). "To test the requirement for adaptive immune responses in eliciting SCC tumor regression, we depleted cytotoxic CD8+ T cells using an α-CD8a antibody that induces antibody-dependent cellular cytotoxicity (ADCC)." (PMID 30832732, 2019). "When the same CAR was constructed with the CD8α transmembrane domain, the anti-tumor efficacy was substantially reduced, owing to the limited expansion and persistence of CAR T cells." (PMID 31108883, 2019). "A pair-wise comparison between the two portions of the same tumor also shows that PD-L1 expression is significantly increased in the portions with higher CD8A expression." (PMID 31523194, 2019). "Consistent with the OS data, the lowest quartile of PDA patients had greater transcriptional expression of cd3e and cd8a, suggesting the presence of more cytotoxic T cells in the tumor." (PMID 30926808, 2019). "Batf3-dependent DCs (CD8α+ or CD103+ DCs) specialize in cross-presentation of necrotic tumor cell-derived epitopes to directly activate CD8+ T cells." (PMID 31324798, 2019). "In contrast to α-PD-1 monotherapy, α-TGFβ antibodies or the drug combination resulted in infiltration of total CD45+ and CD8a + T cells into the tumor core." (PMID 30832732, 2019). "In contrast, all of the B2m−/− mice receiving Batf3−/− spleen DCs, which lack CD8α+ DCs, died from tumor despite the presence of other DC subsets." (PMID 30774630, 2019). "For instance, the levels of CD8A (cytotoxic T‐cell marker) significantly correlated with tumor grade, Ki67 status, and ER status (P = 0.027, P = 0.00019, and P = 0.0022, respectively)." (PMID 30451357, 2019). "CD8+ T-cell tumor infiltration and tumoral gene expression of IFNG, CD8A, CXCL9, and granzyme K (GZMK) were also increased following MEDI0680 administration." (PMID 31439037, 2019). "We treated EMT6-Luc tumor-bearing mice (at 4 weeks post implantation) with one dose of an anti-CD8α antibody or isotype control, after which the primary tumors were resected, and 2 days later, the second dose of an antibody was administered." (PMID 30926774, 2019). "Overexpression of CXCL2 or CCL22, or depletion of CD8a, impaired ttIL-12’s efficacy in suppressing tumor growth and metastasis, which validated the novel mechanism of ttIL-12 in converting a short OS immune profile to a long OS immune profile." (PMID 31208461, 2019). "In tumor samples, we observed many areas with focal expression of PD-L1 and CD8A, suggesting that the CTL-reactive expression of PD-L1 also exists at the intratumor level." (PMID 31523194, 2019). "Cross-presenting Xcr1+CD8α DCs are attractive APCs to target for therapeutic cancer vaccines, as they are able to take up and process antigen from dying tumor cells for their MHCI-restricted presentation to CD8 T cells." (PMID 30863405, 2019). "Overall, the mean and maximum tumor-to-heart ratios of 89Zr-DFO-CD4 and 89Zr-DFO-CD8a were in agreement with flow cytometric analysis of CD4+ and CD8a+ numbers across syngeneic mouse tumor models." (PMID 31754392, 2019). "This adaptive antitumor immune response is characterized by increased differentiation of innate tumor antigen-presenting CD103+/CD8a+ DCs, which subsequently primes and induces tumor-specific CD8+ cytotoxic T cells." (PMID 30683885, 2019). "We observed considerable variations of CD8A expression between different portions of the same tumor sample." (PMID 31523194, 2019).
tumor (continued). "For what concerns other possible predictive biomarkers, high expression on tumor specimens of T- effector and interferon-γ gene signature (defined by CD8A, GZMA, GZMB, IFNγ, EOMES, CXCL9, CXCL10, and TBX21) was related to improved OS in POPLAR study." (PMID 31179334, 2019). "Th17 cells have also been shown to promote the recruitment of CD8α+ DCs in the tumor tissues in the B16 melanoma model." (PMID 31921642, 2019). "Analysis of tumour CD8A expression in the independent validation cohort revealed similar variation in prognostic value across risk strata (PINTERACTION = 0.048)." (PMID 31388185, 2019). "To see if there is a relationship between the predicted neoepitope load from fusions and CD8+tumour-infiltrating lymphocyte (TIL) levels, we used CD8A gene expression from RNA-seq data as an indicator for CD8+TIL level." (PMID 30674975, 2019). "Together, these data indicate that the adoptive transfer of Fcmr−/− DCs promotes more robust anti-tumor responses, mediated through the activation of anti-tumor CD8α+ T cells." (PMID 31213601, 2019). "The tumor-to-blood ratio of 89Zr-DFO-CD8a was significantly lower in CD8a+ depleted mice compared to control mice (5.6 ± 0.03 vs. 8.3 ± 0.32, p=0.011)." (PMID 31754392, 2019). "Mice treated with an isotype antibody effectively cleared the EMT6-luc cells (day 12) and remained tumor-free (day 21), whereas anti-CD8α antibody-treated mice developed pulmonary metastasis and died within 3 weeks." (PMID 30926774, 2019). "TDLNs are the primary sites for cross-priming of CD8+ T cells by CD103+/CD8a+ DCs during tumor growth." (PMID 30683885, 2019). "This response to immune checkpoint therapy as well as relative CD4+ and CD8a+ tumor numbers in syngeneic tumor models were similar to reported elsewhere 54-57." (PMID 31754392, 2019). "MEDI9197 induced an increase in total effector T cells (ratio of Teff (CD45+/TCRβ+/CD44+/CD62L−) to Tnaive/CM (CD45+/TCRβ+/CD44+/−/CD62L+) and effector CD8+ T cells (ratio of CD45+/TCRβ+/CD8α+/CD44+/CD62L− to Tnaive/CM) in the tumor 6–8 days after dosing." (PMID 31511088, 2019). "These facts accord with our results revealing that ApoE KO mice showed more infiltrated CD57+ NK cells and CD8α+ T cells at tumor tissues compared to WT mice." (PMID 31275318, 2019). "Especially cytotoxic (CD8a+) T-cells are an important immunotherapeutic target due to their tumor-killing function." (PMID 31921184, 2019). "IFN-I specifically improves the ability of CD8a+ CD103+ DCs to cross-prime tumor specific CD8+ T cells." (PMID 29619026, 2018). "Specifically, we observed favorable tumor infiltrating lymphocyte expression in these 17 tumor samples from our deconvolution analysis (e.g., more CD8+ T cells, less M0 macrophages) and augmented CD8+ T cell activation expression (e.g., CD8A/B, PRF1, HLA-A)." (PMID 29928512, 2018). "Out of nine proteins with >2-fold higher in expression in HPV-positive tumors, than in HPV-negative tumors, most were surface immunoregulatory proteins that were present on immune or tumor cells (e.g., CD8A, PD-L1, FasL) or chemokines." (PMID 29587383, 2018). "Batf3-dependent CD103+/CD8α+ dendritic cells (DCs) are critical for cross-presenting tumor antigens in tumor draining lymph nodes (TDLNs)." (PMID 30081947, 2018). "The expression of genes related with tumor microenvironment (CD8A, GZMA, and PRF1) can also affect anti-CTLA-4 and anti-PD-1/PD-L1 therapy." (PMID 32793247, 2018). "It was shown that endogenous type I IFN is required to initiate such an antitumor CD8+ T cell response, since mice of which the CD8α+ DCs lack IFNAR are unable to induce lymphocyte-mediated tumor rejection." (PMID 30233579, 2018). "For example, IFN‐I responsiveness controls the ability of CD8α+ cDC1s to cross‐present viral and tumor Ag to CD8+ T cells and also influences DC activation, migration, and T cell priming in vitro." (PMID 28716804, 2017).
tumor (continued). "The maturation of CD8α+ DCs provided prerequisites for the induction of tumor antigen-specific CD8+ cytotoxic T cells." (PMID 28445973, 2017). "In recent years, studies in mice have shed light on the vital dual role played by Batf3+ dependent CD8α+ DCs in mediating anti-tumour adaptive immunity." (PMID 29157300, 2017). "Early produced type I IFNs act on the level of CD8α+ dendritic cells (DCs) that are required for the successful activation of tumor antigen-specific cytotoxic CD8+ T lymphocytes (CTLs)." (PMID 28408907, 2017). "T lymphocytes were extracted from murine spleens, and CD4 and CD8a were identified as the biomarkers of activated cells participating in the anti-tumor immune response." (PMID 28720900, 2017). "Using Batf3+ knock-out mice, Gajewski and colleagues showed that type I IFN-mediated signalling in Batf3+ dependent CD8α+ DCs was critical for the rejection of immunogenic tumours." (PMID 29157300, 2017). "This event, known as T cell priming, is a prerequisite for anti-tumour adaptive immunity relying on activation of CD8α + dendritic cells to promote IFN-I signaling in immature T cells." (PMID 28596706, 2017). "A Shc313F-like signature displays a modestly higher correlation with CD8A (R=0.26) and PD-L1 levels (R=0.28) compared with tumours with an enhanced 2F-like response (R=0.22 and R=0.15, respectively)." (PMID 28276425, 2017). "Apart from functional DC subsets such as CD8α+ DCs, within the tumour microenviroment dysfunctional or tolerogenic DCs such as plasmacytoid DCs (pDCs) have been observed." (PMID 28404796, 2017). "In this study, laminarin-induced maturation of spleen and tumor drLNs and DCs in in vivo tumor microenvironments were investigated, and laminarin-induced maturation of both CD8α+ and CD8α− cDCs promoted Ag specific Th1 and CTL immune responses." (PMID 28423736, 2017). "The percentage of CD8+ T cells recovered from blood, spleen, and tumor that are bound by CD8a-targeting nanoparticles decreases over 24 h but persists for at least 48 h." (PMID 29170511, 2017). "Anti-Nrp-1 not only allowed the increased expansion of tumor-derived CD4+CD8a− T cells, but it also activated tumor-derived CD4+ T cells (CD4+CD69+) in IL-10−/− and WT B16/F10 mice." (PMID 27075020, 2016). "From the tumour-draining LNs we isolated the pDC fraction, a fraction containing all CD8α+ LN-resident DCs, and the CD11bhi DC fraction, and exposed them in vitro to SBAs." (PMID 27819292, 2016). "Human CD141+ DCs are homologous to mouse CD8α+ DCs which are important for anti-viral and anti-tumor immunity." (PMID 27244900, 2016). "CD8α+ cDCs are specialized in cross presentation of Ags via MHC class I to CTLs, and therefore enhancing CD8α+ cDC activation for tumor vaccine has been demonstrated as a new promising strategy in vaccine development." (PMID 27008707, 2016). "The neutralization of Nrp-1 in the IL-10−/− or WT B16/F10 mice resulted in elevated tumor-derived CD8a+ or IFN-γ protein expression in CD8+ T cells." (PMID 27075020, 2016). "Our study showed that ascophyllan induces maturation of spleen and tumor drLN DCs in the tumor environment in vivo, and importantly, that ascophyllan induces maturation of both CD8α+ and CD8α− cDCs." (PMID 27008707, 2016). "Tumor infiltration was measured by flow cytometry for CD8α+ peptide-specific T cells and RT-qPCR for cytotoxic proteins." (PMID 27777777, 2016). "It is reported that type-I IFNs is essential for the maturation of CD11c+ CD8α+ DCs, and these DCs are critical for induction of tumor-reactive T-cell responses." (PMID 27814372, 2016). "Since tumor vaccine needs to induce tumor Ag specific CTL activation for the efficient tumor cell-killing activity, CD8α+ DC-mediated cross-presentation of tumor Ags is crucially important." (PMID 27008707, 2016). "The possible involvement of CD8+ cells in affecting rates of metastasis was studied additionally by tumor staining for CD8a." (PMID 25885274, 2015).